IL17A (interleukin 17A)
Diseases named in the same sentence as IL17A in open-access papers (continued):
Sharing a sentence is not in itself a finding about the gene and the disease.
psoriasis (continued). "In addition, mRNA decreased for both interleukin 17A (IL-17A) and interleukin 19 (IL-19), which are crucial in developing psoriasis." (PMID 38001807, 2023). "Importantly, therapeutic inhibition of aberrant IL-17A and IL-17F activities is used as treatment for skin diseases such as psoriasis and other autoimmune conditions." (PMID 37291218, 2023). "Moreover, IL-23 secreted by dendritic cells and macrophages stimulate γδ T cells to secrete IL-17A, IL-17F, and IL-22 in psoriasis." (PMID 36645209, 2023). "Considering the potential benefits of small molecules over monoclonal antibodies, the next leap forward in treating psoriasis and PsA might be small molecule modulators targeting IL-17A/IL-17RA." (PMID 37731935, 2023). "Our study revealed that there is an overlap between the genes that are differentially expressed in psoriasis patients receiving three anti-IL17A monoclonal antibody drugs and the genes that are differentially expressed in lesion versus non-lesion samples in these patients." (PMID 37816883, 2023). "The role of IL-17A and IL-17F has been established in chronic immune-mediated inflammatory diseases (IMIDs), such as psoriasis (PsO), psoriatic arthritis (PsA), axial spondylarthritis (axSpA), hidradenitis suppurativa (HS), inflammatory bowel disease (IBD), multiple sclerosis (MS), and asthma." (PMID 37600764, 2023). "Our case suggests that IL17A inhibitor treatment may be a culprit agent for eczematous dermatitis in psoriasis patients." (PMID 36820537, 2023). "Mechanistically, the Western diet induces psoriasis-like dermatitis by disrupting the homeostasis of IL-23 and bile acid signaling pathways, promoting γδT cell infiltration at the skin and enhancing their ability to produce IL-17A." (PMID 38033573, 2023). "Because psoriasis is associated with increased lesional TGF-β and IL-17A expression, we next sought to determine whether IL17A+ producing T cells in psoriatic skin differentiate from IL26+ TH17 intermediates and whether this process is driven by TGF-β." (PMID 37391412, 2023). "While the use of monoclonal anti-IL-17A antibodies was disappointing in rheumatoid arthritis and multiple sclerosis, these therapeutics are now used with great success in patients with psoriasis, psoriatic arthritis, and axial spondyloarthritis." (PMID 38299156, 2023). "In addition, CD8+CD103+ TRM cells can be further classified as two subtypes: CD49a-IL-17A+ and CD49a+IFNγ+, assumedly related to psoriasis and vitiligo, respectively." (PMID 37942312, 2023). "Neutrophil-derived IL-17A is a potential drug target for the treatment of psoriasis." (PMID 37920459, 2023). "Thus, application of anti-IL36R antibodies effectively suppressed the development of IL-17A-driven psoriasis-like skin inflammation in these mice." (PMID 38162658, 2023). "Furthermore, tapinarof exhibits direct binding to the aryl hydrocarbon receptor (AhR), leading to a reduction in the production of inflammatory cytokines, including IL-17A, IL-17F, IL-22, IL-23, and IL-1β, as demonstrated in a psoriasis-like mouse model." (PMID 38288335, 2023). "Th17 cells and IL-17A/IL-23 play a crucial role in the immune dysfunction in psoriasis." (PMID 38106405, 2023). "Our results showed that administration of gentamicin alleviated pathogenesis of psoriasis-like symptoms, including alleviating psoriasiform skin inflammation, a decrease in the skin epidermis thickness, decreasing mRNA expression of IL-17A, IL-23, S100A7, and increased mRNA expression of KRT10." (PMID 36710269, 2023). "Both Secukimuab and Ixekizumab target IL-17A, while Brodalumab binds with high affinity to the IL17RA subunit, simultaneously inhibiting IL-17A, IL-17F, IL-17C, and IL-17E and providing a > 95% improvement in upregulated psoriasis genes after 12 weeks of treatment." (PMID 38003284, 2023).
psoriasis (continued). "Glutaminolysis, an abnormal activation mediated by glutaminase 1 (GLS1), promotes Th17 and γδ T17 (IL-17A-producing γδ T cell) cell differentiation by enhancing histone H3 acetylation of the IL17A promoter, leading to an immune imbalance and the development of psoriasis." (PMID 37443834, 2023). "Ixekizumab is a high-affinity, recombinant humanized monoclonal IgG4κ antibody indicated for the treatment of psoriatic arthritis and moderate-to-severe plaque psoriasis by binding specifically to IL-17A and blocking IL-17A activity, reducing inflammation and achieving relief in psoriasis symptoms." (PMID 37920459, 2023). "IL-17A and IL-17F levels were associated with baseline PASI score and psoriasis BSA." (PMID 37587493, 2023). "Effects of an anti-IL-36R antibody treatment were investigated either after establishment of IMQ-induced psoriasis or in keratinocyte-specific IL-17A overexpressing mice (K14-IL17Aind mice), harboring a heterogeneous deletion of the psoriasis-promoting factor IκBζ (Nfkbiz)." (PMID 38162658, 2023). "Similarly, the treatment of psoriasis with Secukinumab, an IL-17A inhibitor, also alleviates psychological symptoms of ASD in humans." (PMID 37920540, 2023). "Moreover, the discovery of Th17 subsets and IL-23 has revealed the involvement of the IL-23/IL-17A axis in the pathogenesis of psoriasis." (PMID 37964882, 2023). "For peripheral inflammation, it has been shown that disruption of the expression and activation of the IL-17RA/IL-17RC complex on Th17 cells increases IL-17A production and leads to an accelerated course of experimental sickle-shaped glomerulonephritis, psoriasis, and colitis." (PMID 38067176, 2023). "Similarly, the qPCR analysis indicated that the expression of psoriasis-related cytokines, such as IL-17a and IL-17f, was significantly lower in Slc35e1−/− mice than in control animals." (PMID 37296095, 2023). "Therefore, administration of an antibody against IL-17A, commonly used in psoriasis treatment, decreases fasting glucose levels and restores islet functions in IMQ mice." (PMID 37762754, 2023). "Furthermore, mice with epidermal TGF-β1 overexpression develop severe IL-17A-dependent psoriasis-like skin disease." (PMID 37391412, 2023). "Under the condition of abundant IL-23 in psoriasis lesional skin, some macrophages may produce IL-17A, IL-22 and IFN-γ in addition to TNF-α as described in our previous review article." (PMID 38022549, 2023). "After demonstrating that AOA reduces inflammation by inhibiting serine metabolism in Th17-mediated psoriasis, we investigated whether this drug could also reduce the inhibition of serine metabolism and IL-17A production in mouse primary Th17 cells." (PMID 37649889, 2023). "Since previous studies showed that αβ T cells synergistically enhanced IMQ-induced IL-17A responses in inflammatory diseases, such as psoriasis 37, we next tested whether this response might be involved in DSS-induced colitis." (PMID 37284442, 2023). "However, when comparing the numbers of IL17A+ cells, we found only few IL17A+ cells in AD compared to psoriasis." (PMID 37391412, 2023). "Our finding also suggests that blocking IL-26 may be a beneficial approach to intervene in conditions which manifest exaggerated IL-17A responses in epithelial tissues including TH17 diseases such as psoriasis." (PMID 37391412, 2023). "Treatment with secukinumab, which targets IL-17A, decreases activation and chemokine production in neutrophil-induced skin lesions, indicating that IL-17A from this cell type may be involved in exacerbating psoriasis." (PMID 37964882, 2023). "This aligns with the normalization of CXCL12 serum level after therapeutic targeting of IL-17A and may provide an explanation for the decreased level of CXCR4hi neutrophils following effective psoriasis treatment." (PMID 37736772, 2023).
psoriasis (continued). "Since neutrophils and mast cells staining positive for IL-17 were identified at higher densities than IL-17+ T cells in psoriatic lesions, neutrophils and mast cells are considered other significant potential sources of IL-17A in psoriasis." (PMID 38022549, 2023). "Both anti-TNF and CsA agents reduced the levels of IFN-c, IL-17A, IL-23p19, and (C–C motif) chemokine ligand 20 in psoriasis lesions, indicating that pro-inflammatory cytokines, particularly IL-17A, are involved in the development of psoriasis." (PMID 36995575, 2023). "In this review, we will summarize the current knowledge around IL-17A and its five currently known homologues, namely IL-17B, IL-17C, IL-17D, IL-17E (also known as IL-25) and IL-17F, in relation to skin inflammation in general and psoriasis in particular." (PMID 37283755, 2023). "In addition, an adiponectin-derived peptide, P5, which acts through the AdipoR1 receptor, was found to inhibit IL-17A mRNA expression in γδ-T cells and alleviate imiquimod-induced psoriasis in mice." (PMID 37047363, 2023). "On the upper hand, exosome-based delivery of miR-340 might be capable of attenuating psoriasis by directly targeting IL-17A." (PMID 37108809, 2023). "Dermal injection of psoriasis biomarker IL-23 directly into mice results in the development of skin inflammation driven by Th17 cells (the same as in human psoriasis) and upregulation of pro-inflammation cytokines (IL-22, IL-17A, INF-γ)." (PMID 37298466, 2023). "In studies involving the IMQ mouse model, a marked elevation of Tbxar2 mRNA expression has been observed in Vγ4+ γδ T cells, which facilitates the enhanced secretion of IL-17A in these T cells, ultimately contributing to the manifestation of skin lesions reminiscent of psoriasis." (PMID 38035065, 2023). "Monoclonal antibodies against IL-17A, such as Ixekizumab, Secukinumab, and Bimekizumab have been widely used clinically in immune-mediated inflammatory diseases such as psoriasis, psoriatic arthritis, and axial spondyloarthritis, showing high selectivity and safety." (PMID 37978543, 2023). "Results: we externally applied BZLF for skin lesions in an imiquimod-induced psoriasis mouse model and found that BZLF alleviated psoriasis-like skin lesions while inhibiting the expression of Ki67 and inflammatory factors (Il17a, Tnf-α, S100a7 and Cxcl1) in skin lesions." (PMID 36950008, 2023). "To validate the spatial specificity of these responses, we calculated the keratinocyte subtype module scores as well as IL-17A and IL-36γ module scores and projected these scores to 10 μm-sided square grids on a psoriasis skin biopsy specimen processed by Seq-Scope21 (see the “Methods” section)." (PMID 37308489, 2023). "TNF-α and IL-17A act in a synergic manner to maintain the cytokine cascade in psoriasis." (PMID 38003284, 2023). "Ligilactobacillus and Anaeroplasma (inhibited in CUR mice) were positively correlated with multiple psoriasis‐related factors, such as IL‐6, IL‐17A, IL‐22, IL‐23, while Rikenella, Alistipes, and Mucispirillum (promoted in CUR mice) were negatively correlated with them." (PMID 37647442, 2023). "Galectin-7 expression is low in psoriasis and enhances keratinocyte sensitivity to IL-17A.." (PMID 37762693, 2023). "Furthermore, cytokine-stimulated HaCaT cells are commonly used to simulate psoriasis in vitro, and there is evidence that psoriatic inflammation depends on the synergistic effect of multiple cytokines, particularly IL17A." (PMID 37076497, 2023). "Notably, agents targeting tumor necrosis factor (TNF), IL-12/IL-23 p40 subunit, IL-17A, and IL-17RA have gained approval for treating psoriasis." (PMID 38137572, 2023). "Both IL-17A and -F belong to the IL-17 cytokine family that helps to control infections but also plays a role in various chronic inflammatory conditions such as human psoriasis and rheumatoid arthritis." (PMID 37486897, 2023).
psoriasis (continued). "However, the effectiveness of TNF-α inhibitors in psoriasis is based on indirect adaptive immune modulations, especially on the IL-23/IL-17A axis." (PMID 38239345, 2023). "However, IL-17A can induce keratinocytes to express K17, which is abnormally overexpressed in psoriasis." (PMID 37594540, 2023). "IL-17A inhibition was shown to exhibit a faster mode of onset compared to IL-23 inhibition, which is in line with the idea that blocking a “downstream” effector cytokine such as IL-17A should reduce psoriasis symptoms faster than blocking an “upstream” regulatory cytokine such as IL-23." (PMID 37283755, 2023). "Here, our data suggest that CD8+ T cells are a major source of IL17A in psoriasis." (PMID 37308489, 2023). "IL-23 and IL-17A are pivotal inflammatory factors in the pathogenesis of psoriasis, with IL-23 promoting the secretion of IL-17 and IL-21 by Th17 cells, enhancing neutrophil infiltration and inducing inflammation in psoriasis." (PMID 38239345, 2023). "In our study, PTG1, HMMR, PBK, FEN1, DEPDC1 may be some psoriasis-related genes in IL-17A treating of psoriasis." (PMID 37029373, 2023). "Having shown that AD contains similar high numbers of IL26+ TH17 intermediates but lower expression levels of epidermal TGF-β1 and reduced numbers of IL17A+ cells when compared to psoriasis, we sought to compare the location of IL-26 expression in both diseases using spatial transcriptomics." (PMID 37391412, 2023). "IL17A inhibition has emerged as a promising therapeutic strategy in patients with extensive or refractory BP but paradoxical development of BP after secukinumab treatment for psoriasis has also been described." (PMID 37077669, 2023). "Notably, in psoriasis patients treated with an anti-interleukin (IL)-17A biologic (secukinumab), CXCR4 expression on circulating neutrophils was reduced over a 12-weeks period treatment and was concomitant with a decrease in overall disease activity." (PMID 37736772, 2023). "Moreover, a large pool of TRM cells express IL-17A alone, IL-17A and IL-22, or IL-22 alone, and persist in post-lesional psoriasis skin." (PMID 36901778, 2023). "Thus, a decreased level of miR-1910-3p abolishes the suppressive effect of its target gene IL-17A, accelerating the progression of psoriasis by increasing the levels of pro-inflammatory molecules and promoting the proliferation of keratinocytes." (PMID 37554338, 2023). "Clinical trials have shown that inhibiting IL-17A in patients with psoriasis could potentially contribute to the improvement of metabolic and liver parameters." (PMID 36836776, 2023). "Anti–PD-1 immunotherapy, although effective against some melanomas, can also exacerbate psoriasis and colitis, but IL-17A blockade may reverse these toxicities." (PMID 36480166, 2023). "Furthermore, psoriasis-related factors, such as IL-17A, IL-17F, IL-22, and IL-23R, can be transcriptionally activated by STAT3, suggesting that STAT3 plays a promoting role in psoriasis development." (PMID 36835162, 2023). "In a recent study, miR-378a ectopic overexpression, mimicking the miRNA increase in psoriasis, was found to promote p63 transport to the nucleus and further contributed to the IL-17A-mediated activation of NF-κB pathway signaling by acting as suppressor of NFKBIA." (PMID 36174034, 2022). "In addition, γδ T cells/IL-17A axis is also closely related to diseases such as psoriasis and bronchial asthma." (PMID 35371044, 2022). "In addition to the reported effect of CaMK4 on IL-17A production, we also document that CaMK4 has functions in dermal macrophages and epidermal KCs to affect psoriasis progression." (PMID 35869084, 2022). "Individuals with psoriasis were shown to display elevated IL-17A, and the imiquimod model of skin inflammation is reliant on the induction of IL-17A, which has been reported to act on keratinocytes and induce neutrophil attraction and contribute to skin inflammation." (PMID 36477177, 2022).
psoriasis (continued). "Moreover, the potential role in distinguishing between early-onset and late-onset psoriasis: we obtained serum IL-17A, serum Claudin-1, and their combination AUC of 0.590 (p = 0.3126), 0.741 (p = 0.0045), and 0.741 (p = 0.0067), respectively." (PMID 35340911, 2022). "A previous study indicated the crucial role of IL-17A in the pathogenesis of human psoriasis." (PMID 35055377, 2022). "The aim of the current investigation was to estimate serum IL-17A and Claudin-1 levels in psoriasis, detect their correlation with disease severity, and examine whether they are blood-based candidate biomarkers associated with psoriasis and subtypes." (PMID 35340911, 2022). "IL-17A effectively inhibits the function of osteoblasts and osteocytes in patients with psoriasis." (PMID 34980884, 2022). "Blocking IL-23 or IL-17A shows highly clinical efficacy in the treatment of psoriasis." (PMID 36419191, 2022). "Chemokines such as CCL20 and MCP-3/CCL7 are stimulated by Th17 cell cytokines, e.g., IL-17A, which may contribute to a positive IL-17 response feedback loop in psoriasis." (PMID 35008981, 2022). "The mouse model of imiquimod (IMQ)-induced psoriasis is a well-established animal model for psoriasis study and has been confirmed to resemble human psoriasis in the mechanism of pathogenesis and immunity, including a major involvement of the IL-23/IL-17A axis." (PMID 36620087, 2022). "To test this hypothesis, we first measured IL-17A expression in blood neutrophils by Western blot and found that the protein expression of IL-17A was more enriched in neutrophils from psoriasis patients than those from healthy controls." (PMID 35401573, 2022). "Moreover, a large pool of α/β TRM cells expressing IL-17A alone, IL-17A and IL-22, or IL-22 alone persist in post-lesional psoriasis skin." (PMID 36361639, 2022). "Psoriasis is an inflammatory skin disease mediated by elevated IL-17A levels in patient serum." (PMID 34980884, 2022). "In conclusion, the dual neutralization of IL-17A and IL-17F can be efficacious for fast and sustainable management of psoriasis in a real world setting, even in special skin localizations such as the scalp or the groins, when the blocking of IL-17A, IL17-RA or IL-23 has previously failed." (PMID 36614836, 2022). "Moreover, the anti-inflammatory activity of active constituents on a TNF-α/IL-17A/IFN-γ-stimulated human keratinocyte psoriasis model was also evaluated." (PMID 36015080, 2022). "In another mouse model (K14-IL-17Aind/+) investigating IL-17A overexpression in keratinocytes inducing psoriasis-like lesions, evidence of vascular dysfunction and arterial hypertension, along with large aortic wall cellular infiltrates and reduced survival compared to the controls, was observed." (PMID 36012327, 2022). "Subsequently, we demonstrated that TC could regulate IL-17A-induced inflammation and cell proliferation via the mTOR/p70S6K and NF-κB signaling pathways and, thus, may play a role in the pathogenesis of psoriasis." (PMID 36498953, 2022). "Notably, psoriasis is mediated by T-cell effector cytokines, including IL-17A, IL-22, and TNF-α, which induce antimicrobial peptides in keratinocytes and neutrophils." (PMID 36232814, 2022). "The Th1 (TNF-α) and Th17 (IL-17A and IL-22)-related cytokines are important proinflammatory cytokines, involved in maintenance of chronic inflammatory response and epithelial tissues remodeling in psoriasis pathogenesis." (PMID 36741386, 2022). "Significantly higher IL-17A and lower Claudin-1 levels were found in psoriasis (p < 0.05)." (PMID 35340911, 2022). "Regarding inhibitory cytokines, several studies have found decreased expression of IL-38 in both skin and blood of psoriasis patients, whereas its expression was increased in normal skin and upregulated in lesional psoriasis following treatment with anti-IL-17A biologic agents." (PMID 36012744, 2022).